HPGD (15-hydroxyprostaglandin dehydrogenase)
Diseases named in the same sentence as HPGD in open-access papers (continued):
Sharing a sentence is not in itself a finding about the gene and the disease.
skin aging (1 paper, 2023). The gradual irreversible changes in structure of skin that occur as a result of the passage of time.. "Molecular docking analysis showed that 8 key compounds had a high docked ability with AR, BCHE, HPGD and PI3, which were identified as specific biomarker for the diagnosis of skin aging." (PMID 37310405, 2023). "Then, we confirmed the down-regulated expressions of ABCC4, PTGER3, BCEH, HPGD, and MOXD1 in normal group, while AR, CXCR2, HSD17B2, ODC1, PI3, PLAU and THBS2 were up-regulated in skin aging group." (PMID 37310405, 2023). "In addition, ROC curve verified that these hub-target had certain sensitivity and specificity for the diagnosis of skin aging (AUC greater than 0.5), AR, BCEH, CXCR2, HPGD and PI3 performed well especially." (PMID 37310405, 2023).
soft tissue tumors (1 paper, 2019). "In this study, we reported the first case of HPGD-mutated PHO patient, presenting typical PHO features and atypical soft tissue tumors at bilateral lower legs." (PMID 31063976, 2019).
viral infection (1 paper, 2021). "Also, the ex vivo infection of living human PCLS with SARS-CoV-2 (viral infection analyzed by NSP7 qRT-PCR) led to an upregulation of COX-2 expression compared with non-infected control slices, while HPGD mRNA levels were unchanged and PGE synthase (PTGES) expression tended to be increased." (PMID 34347801, 2021).
tumor (80 papers, 2011 to 2025). "Elevated COX-2 activity has been previously associated with decreased HPGD levels, suggesting a reciprocal relationship that can drive tumor progression." (PMID 40728977, 2025). "The downregulation of HPGD is associated with increased levels of PGE2 in the tumour microenvironment, leading to the increased proliferation and survival of hepatocytes, which contributes to the development of HCC from metabolic dysfunction-associated steatohepatitis." (PMID 40535770, 2025). "Six hits in five genes [AK3 (rs378117), TRPM3 (rs1329774 and rs4745058), CDH4 (rs2427043), LINC00504 (rs76228864), and GRIN2D (rs76754767)] were associated with a risk of tumour progression, whereas variants in HPGD (rs45593131) and RC3H2 (rs2792999) were suggested as protective factors." (PMID 40535770, 2025). "In this study, we investigate the functional roles of HPGD in the regulation of tumor growth and phenotypic changes in TNBC, focusing on both human and murine TNBC cell lines following ectopic HPGD expression." (PMID 40076539, 2025). "For instance, hydroxyprostaglandin dehydrogenase 15-(NAD) (HPGD) participates in the degradation and metabolism of Prostaglandin E2 (PGE2), which is implicated in inflammation response and tumor proliferation." (PMID 40428349, 2025). "By day 21, the tumors in the HPGD-overexpressing group were notably larger, indicating that HPGD overexpression enhances tumor growth in this xenograft model." (PMID 40076539, 2025). "Sun and colleagues first established the ENO1-YAP1/PLCB1/HPGD regulatory axis, demonstrating its glycolytic-independent mechanism in promoting tumor growth via arachidonic acid (AA) metabolic reprogramming." (PMID 41353343, 2025). "Increased CHSY1 and CSGALNACT2 expression remodels the extracellular matrix (ECM) through glycosaminoglycan biosynthesis, whereas downregulation of HPGD induces prostaglandin-driven inflammation, both of which are critical for tumor progression." (PMID 40626022, 2025). "Further reinforcing the clinical relevance of cfRNAs, studies have shown that HPGD’s involvement in the prostaglandin metabolic pathway is crucial for understanding its impact on tumor growth and the inflammatory microenvironment surrounding cancers." (PMID 40728977, 2025). "HPGD (15-Hydroxyprostaglandin dehydrogenase), an important enzyme regulating the metabolism of prostaglandins, has been confirmed as a tumor suppressor in many malignancies." (PMID 36776317, 2023). "The expression levels of the 15-hydroxyprostaglandin dehydrogenase (15-PGDH) tumor suppressor were also higher in the Nrf2-knockout group than in the wild-type, which only supports the oncogenic effects of Nrf2 in the later stages of colonic carcinogenesis." (PMID 36837862, 2023). "HPGD has a significantly lower expression in in-house CRC tumor samples (p-value=4.63e-07, log2Fold-Change=-2.70) and pre-surgical cfRNA (p-value=1.67e-02, log2Fold-Change=-0.74)." (PMID 37091184, 2023). "Four genes (BDNF, PTGS2, GSK3B, and CTNNB1) were significantly upregulated and one gene (HPGD) was significantly downregulated in primary tumor tissues compared with adjacent normal tissues throughout all the five in silico datasets." (PMID 35054980, 2022). "One of the genes (HPGD) was eliminated from the five-gene signature due to its very low expression in the tumor samples compared to its matched normal tissue, which makes it not suitable for detection in plasma samples from CRC patients." (PMID 35054980, 2022). "Several studies have demonstrated that HPGD functions as a tumor suppressor gene in various cancers." (PMID 35317779, 2022). "The tumor suppressor 15-hydroxyprostaglandin dehydrogenase (15-PGDH) is an enzyme responsible for the degradation of PGE2 into an inactive metabolite." (PMID 36045676, 2022).
tumor (continued). "Finally, HPGD which encodes the PGE2 signal terminator 15-PGDH is significantly upregulated in the CD44+/CD24- tumor cells; this could negate any increased production of PGE2 cells due to increased PLA2/COX-2, since increased 15-PGDH would degrade produced PGE2." (PMID 35127497, 2021). "15-hydroxyprostaglandin dehydrogenase (HPGD) serves as a tumor suppressor by converting prostaglandins into inactive forms and inhibiting prostaglandin-endoperoxide synthase." (PMID 33435156, 2021). "Downregulation of HPGD has been shown in several malignancies including lung, colon, bladder, endometrial, and gastric cancer and has been shown to have a tumour suppressor roles in some settings." (PMID 33210098, 2020). "Intriguingly, while HPGD has been widely reported as a tumor suppressor in multiple types of cancer, it is selectively enriched in the malignant cells of both tissue sections 1.2 and 2.4." (PMID 32103057, 2020). "miR-620 is reported to up-regulate PGE2 expression by directly targeting HPGD, contributing to tumor radiation resistance." (PMID 30333561, 2018). "The tumor suppressor 15-hydroxyprostaglandin dehydrogenase (15-PGDH) is a key enzyme in PGE2 catabolism, converting it into its inactive metabolite 15-keto-PGE2, and is often down-regulated in cancer." (PMID 28402256, 2017). "However, other studies suggest that HPGD can act as a tumor promoter, as inhibition of HPGD has been shown to increase tumorigenesis, including invasion and metastasis, through processes like EMT." (PMID 40076539, 2025). "Conversely, downregulation of FBP1 and HPGD, coupled with their hypermethylation, reinforces the metabolic shift toward glycolysis and potentiates prostaglandin-driven inflammation, both of which are key drivers of tumor progression." (PMID 40626022, 2025). "In contrast, other models demonstrated that ablation of Nrf2 reduced aggressive tumor formation and upregulated tumor suppressors such as 15-hydroxyprostaglandin dehydrogenase (15-PGDH), suggesting that in later stages Nrf2 may facilitate tumor growth." (PMID 41462607, 2025). "The HPGD gene is recognized as a tumour suppressor in various cancers, including HCC." (PMID 40535770, 2025). "The tumor suppressive role of HPGD has been observed in several cancers." (PMID 35317779, 2022). "Conversely, expression downregulation in tumor tissue was observed for genes encoding components of the pathway leading to the signaling of other prostanoids, but most notably of HPGD that encodes the PGE2-inactivating enzyme 15-PGDH." (PMID 32410997, 2020). "Notably, tumor-infiltrating myeloid cells were also characterized by down-regulated expression of the major PGE2-catabolizing enzyme 15-hydroxyprostaglandin dehydrogenase (15-PGDH)." (PMID 31811337, 2020). "As a cancer suppressor, the expression level of HPGD is decreased in several tumour cells." (PMID 30404616, 2018). "Evidence also suggests that HPGD (15-PDGH) expression levels in normal colon and the germline rs6983267 polymorphism that relates to tumor CTNNB1 (β-catenin)/WNT signaling status may predict the efficacy of aspirin for cancer chemoprevention." (PMID 29552640, 2017). "However, other studies have shown that low HPGD expression correlates with poor prognosis, increased cancer invasion, migration, and resistance to certain therapies, further complicating its role as a potential tumor suppressor or promoter." (PMID 40076539, 2025). "It was indicated that the N-M tumor metastasis pattern and a putative ovarian origin, rather than tubular origin, are associated with a more favorable prognosis, which would be in line with a role of SLCO2A1 and HPGD implicated in the degradation of pro-inflammatory prostaglandins." (PMID 30131693, 2018). "The oncogenic components, namely, ALDH1B1, ALDH1L2, CHSY1, CSGALNACT2, and GPX8, were progressively upregulated in more aggressive tumors, while the tumor suppressor hubs FBP1 and HPGD were downregulated as tumor aggressiveness increased." (PMID 40626022, 2025).
tumor (continued). "CDCA7, CELSR3, PACS1, SNTB1, and TBC1D31 showed consistent upregulation in CRC tumor samples and pre-surgical cfRNA, while GFI1B, HPGD, SH3BGRL2, SIAE, PKHD1L1, and TDP2 showed downregulation in CRC tumor samples and pre-surgical cfRNA." (PMID 37091184, 2023). "Clinical samples showed significant downregulation of the following genes: CPT2, ACAA2, HPGD and ALDH3A2, while the expression of ENO2, TDO2, CPOX, ACADL and PTPRG was significantly upregulated in the tumor tissue (p < 0.01)." (PMID 36230866, 2022). "The expression levels of the distinct genes of the RvD pathway ALOX15, ALOX15, FPR2, GPR18, GPR32, HPGD and PTGR1 were leveraged from 516 bulk tumor HNSC RNA-seq data, profiled by TCGA and plotted as a heatmap of individual tumor samples." (PMID 35742918, 2022). "Shh inhibitors also exert an anti-proliferative function by elevating 15-hydroxyprostaglandin dehydrogenase (15-PGDH), a prostaglandin E2 (PGE2)-degrading and tumour-suppressive enzyme, which subsequently inhibits cyclooxygenase-2 (COX-2)." (PMID 34702800, 2021). "IL-1β derived from TAMs suppresses the expression of 15-hydroxyprostaglandin dehydrogenase (15-PGDH), an enzyme involved in prostaglandin degradation in PDAC cells, which results in tumor growth and poor prognosis for PDAC patients." (PMID 32635472, 2020). "PTGDS (Prostaglandin D2 Synthase) and HPGD (15-Hydroxyprostaglandin Dehydrogenase) are enriched in the tumor region, while MGST3 (Microsomal Glutathione S-Transferase 3) is depleted in the tumor region in tissue section 1.2." (PMID 32103057, 2020). "We found an upregulation for the PTGS2 gene mean factor of 2.51 and a downregulation for the HPGD and SLCO2A1 genes (mean factor of 0.10 and 0.37, respectively) in tumorous mucosa in a gender-independent manner." (PMID 33081378, 2020). "These genes are known to be implicated in proliferation (MAPK8), metastatic diffusion of tumor cells (ITGB1), drug resistance (ANXA1), coagulation (ANXA3, ANXA5) or inflammation (HPGD, NFKB1)." (PMID 29228619, 2017). "Myung and coworkers showed that the deletion of the 15-PGDH gene HPGD increases colonic PGE2 levels and enhances tumorigenesis in vivo, demonstrating the tumor suppressor effect of 15-PGDH." (PMID 28402256, 2017). "The synthesis of tumor-promoting prostaglandins is regulated not only by PTGS-2, but also by the PGE2-catabolizing enzyme HPGD, which acts as a physiological antagonist to PTGS-2." (PMID 28143522, 2017). "While HPGD may act as a tumor suppressor in some contexts, its role in TNBC is species- and cell line-dependent for proliferation and tumor growth." (PMID 40076539, 2025). "Our analysis shows a significant correlation between PACS1 and HPGD expression levels post-operation, suggesting that PACS1 may act to regulate the HPGD expression in response to changes within the tumor microenvironment." (PMID 40728977, 2025). "The levels of PGE2 in tumor tissues depend on the relative rates of PTGS2 (COX-2)/PGE synthase-dependent biosynthesis and hydroxyprostaglandin dehydrogenase 15-(NAD) (HPGD, also called as 15-PGDH)-dependent degradation." (PMID 24213116, 2011). "First, the reversal of epigenetic silencing, potentially through the use of DNA methyltransferase inhibitors, could restore the expression of tumor suppressor metabolic hubs such as FBP1 and HPGD, thereby rebalancing cellular metabolism and limiting tumor progression." (PMID 40626022, 2025). "We set out to validate the expression of the three cfRNA biomarkers – HPGD, PACS1, and TDP2 identified in our in-house cfRNA and CRC tissue samples using an independent cohort of pre- and post-surgical cfRNA samples (N=36) and published TCGA CRC tumor and tumor-adjacent samples (N=453)." (PMID 37091184, 2023).
cancer (52 papers, 2008 to 2025). A tumor composed of atypical neoplastic, often pleomorphic cells that invade other tissues. "Among these, HPGD, known to be significantly associated with cancer development, drew our attention." (PMID 30333561, 2018). "The deregulation of genes like PTGS2 (COX-2) and HPGD (15-PGDH) could be the drivers behind the prostaglandin-induced cell changes associated with cancer." (PMID 35127497, 2021). "Collectively, these observations underscore the complexity of HPGD’s role in cancer, with its function likely depending on the tissue type, stage of the disease, and other molecular factors that modulate its activity." (PMID 40076539, 2025). "Collectively, these findings highlight the complex and context-dependent role of HPGD in cancer biology." (PMID 40076539, 2025). "Our results highlight the diverse roles of HPGD in cancer biology, particularly in the context of TNBC, and point to non-enzymatic pathways as a significant aspect of its tumorigenic activity." (PMID 40076539, 2025). "Prostaglandin regulation is known to play a pivotal role in tumorigenesis; however, the contributions of the prostaglandin-metabolizing enzyme 15-hydroxyprostaglandin dehydrogenase (HPGD) to cancer development remain poorly understood." (PMID 40076539, 2025). "The role of HPGD in tumorigenesis has been reported to vary across different cancer types, further supporting the idea that its function is tissue dependent." (PMID 40076539, 2025). "The identification of HPGD’s potential role in modulating KRAS signaling pathways further supports its involvement in cancer progression." (PMID 40076539, 2025). "Among the enriched CCs, The cytoplasm (associated with 6 KGs: OAS1, OAS3, IRF9, HPGD, TP53INP1 and NQO1) has been found to be associated with most proteins that are highly expressed for cancer." (PMID 35617355, 2022). "This promoter has also been used to control 15-hydroxyprostaglandin dehydrogenase (15-PGDH) gene expression, a repressed gene in most cancers." (PMID 33381459, 2020). "Vitamin D affects genes regulating proliferation, apoptosis, and differentiation and induces the tumor suppressor 15-hydroxyprostaglandin dehydrogenase (PGDH) in other cancers." (PMID 28922414, 2017). "Consistent with the antitumorigenic effect of HPGD, the down-regulation of HPGD has been observed in many human cancer types." (PMID 27561985, 2016). "It is worth noting that the effect of miR-21 on HPGD expression has also been observed in other cancer type." (PMID 27561985, 2016). "This revealed up to 12 genes that are suppressed in CRC, including genes that had been previously found misregulated in cancer, such as HPGD, PTGIS, PTGER3, and AKR1B1." (PMID 26207152, 2015). "HPGD is the key enzyme that inactivates a number of bioactive lipids, and is also a tumor suppressor; its expression is reduced in a range of human cancers relative to corresponding normal tissue." (PMID 26068950, 2015). "The vector was used to transfect mouse murine forestomach carcinoma (MFC) cancer cells and observe the effects of 15-hydroxyprostaglandin dehydrogenase (15-PGDH) on the proliferation of MFC." (PMID 24348808, 2014). "Although the expression of the 15-hydroxyprostaglandin dehydrogenase (HPGD) gene and miR-106b-5p are reportedly linked to cancer progression, their underlying mechanisms in ESCC remain unclear." (PMID 35317779, 2022). "It is possible that this apparent difference in the miR-21 effect on HPGD expression may be due to differences in cancer types." (PMID 27561985, 2016). "A total of five cancer-related genes (BDNF, PTGS2, CTNNB1, GSK3B, and HPGD) were selected based on the Gene Ontology database." (PMID 35054980, 2022). "The expression of TF-protein FOXL1 (a regulator of NT5E, TP53INP1, HPGD, FN1, OAS1 and NQO1) is connected with numerous cancer." (PMID 35617355, 2022). "15-hydroxyprostaglandin dehydrogenase (15-PGDH) is an antagonist of COX-2 and exerts a strong inhibitory effect on the development of cancer." (PMID 30216977, 2018).
cancer (continued). "Deregulations of miR-21 and miR-130b, as well as deregulation of GPD1L, HLF, HPGD and MGLL have been reported either in HNOC or other cancer types, and these MRMs represent significant functional relevance in OTSCC." (PMID 27561985, 2016). "Together, our results provide support for a model whereby miR-620 targets HPGD, resulting in accumulation of HPGD's substrate, PGE2, and signaling by PGE2 through the EP2 receptor results in cancer radiation resistance." (PMID 26068950, 2015). "Vitamin D modulates molecular pathways relevant to CRC development, including the downregulation of the COX-2 gene and the upregulation of 15-hydroxyprostaglandin dehydrogenase (15-PDGH), leading to a reduction in local prostaglandin levels and hence inhibiting cancer cell survival." (PMID 38542719, 2024). "Our recent research showed that NAD+ decline promoted epithelial-mesenchymal transition (EMT), migration, and invasion of cancer cells by activating the STAT3 signaling pathway and oxidatively degrading 15-hydroxyprostaglandin dehydrogenase (15-PGDH, an NAD+-dependent enzyme) via accumulated ROS." (PMID 35338115, 2022). "HPGD is a known anti-tumorigenic effecter, and it regulates the tumorigenic actions of Prostaglandin E2 (PGE2) by converts PGE2 to its biologically inactive metabolite, and down-regulation of HPGD has been observed in many human cancer types." (PMID 27561985, 2016). "The enzyme 15-PGDH, which in humans is encoded by the HPGD gene located on chromosome 4, plays a key role in breaking down PGs and is highly expressed in normal tissues but is often absent in several types of human cancers, including CRC." (PMID 41465616, 2025). "The degradation of prostaglandins (PG) by 15-hydroxyprostaglandin dehydrogenase (15-PGDH) is one of the crucial steps in regulating PG levels, especially prostaglandin E2 (PGE2), which is known to play major roles in carcinogenesis, cancer progression, and tissue regeneration." (PMID 30531928, 2018). "However, the role of HPGD in cancer biology has not been adequately addressed to date." (PMID 30333561, 2018).
infection (4 papers, 2021 to 2023). The state of being infected such as from the introduction of a foreign agent such as serum, vaccine, antigenic substance or organism. "Only HPGD, PACS1, and TDP2 showed involvement in biological pathways, including metabolism, infection, and DNA repair-related pathways." (PMID 37091184, 2023).
adenocarcinoma (3 papers, 2009 to 2015). A common cancer characterized by the presence of malignant glandular cells. "In the case of RECK, CRISPLD2, HPGD, GATA3 and GPC3, the signal related to the expression of the protein was down regulated in more than 45% of adenocarcinomas compared to surrounding healthy pneumocytes." (PMID 24265725, 2013). "In particular Hpgd (15- hydroxyprostaglandin dehydrogenase) was significantly −23.1-fold down regulated in adenocarcinoma vs transgenic and −26.6-fold down regulated in adenocarcinoma vs non-transgenic cells." (PMID 19812696, 2009).